HECTD2 (HECT domain E3 ubiquitin protein ligase 2)
Description:
E3 ubiquitin-protein ligase which accepts ubiquitin from an E2 ubiquitin-conjugating enzyme in the form of a thioester and then directly transfers the ubiquitin to targeted substrates. (Microbial infection) Catalyzes ubiquitination of Botulinum neurotoxin A light chain (LC) of C.botulinum neurotoxin type A (BoNT/A).
Synonyms: FLJ37306
Tractability: PROTAC: ubiquitination databases record sites on it.
Gene: Protein-coding gene on chromosome 10 (91,409,280 to 91,514,829, forward strand). Ensembl gene ENSG00000165338.
Subcellular location (Human Protein Atlas): Nucleoplasm
Pathways (Reactome):
Immune System: Antigen processing: Ubiquitination & Proteasome degradation
Gene Ontology:
Molecular function: ubiquitin protein ligase activity; ubiquitin-protein transferase activity
Biological process: protein polyubiquitination; protein ubiquitination
Cellular component: cytosol
Genetic constraint (gnomAD): Loss-of-function variants: 4 observed, 17.11 expected, observed/expected ratio (o/e) 0.23, 90% interval 0.11 to 0.54. The upper end of that interval is the gene's LOEUF score, 0.54, which puts it in group 2 of 6, group 1 being the genes least tolerant of losing a copy. Missense variants: 154 observed, 222.13 expected, observed/expected ratio (o/e) 0.69, 90% interval 0.61 to 0.79. Synonymous variants: 87 observed, 83.94 expected, observed/expected ratio (o/e) 1.04, 90% interval 0.87 to 1.24.
Homologues: Orthologues: chimpanzee HECTD2 (99% identical), macaque HECTD2 (98% identical), pig HECTD2 (94% identical), dog HECTD2 (94% identical), guinea pig HECTD2 (91% identical), rat Hectd2 (90% identical), mouse Hectd2 (89% identical), tropical clawed frog hectd2 (80% identical), zebrafish hectd2 (73% identical), rabbit HECTD2 (53% identical). Paralogues in human: HERC3 (24% identical), HERC4 (24% identical), HECW1 (23% identical), ITCH (23% identical), WWP1 (23% identical), UBE3A (23% identical), HUWE1 (23% identical), AREL1 (23% identical), HECW2 (22% identical), WWP2 (22% identical), NEDD4 (22% identical), NEDD4L (22% identical), and 12 more.